DCN (decorin)
Description:
May affect the rate of fibrils formation.
Synonyms: SLRR1B; DSPG2; CSCD; PG40; PGII; PGS2
Tractability: Antibody: UniProt places it where antibodies can reach, with high confidence; its Gene Ontology location is reachable by antibodies, with high confidence; UniProt predicts a signal peptide or a membrane-spanning region. PROTAC: ubiquitination databases record sites on it; its protein half-life has been measured.
Gene: Protein-coding gene on chromosome 12 (91,140,484 to 91,183,217, reverse strand). Ensembl gene ENSG00000011465.
Subcellular location: Secreted, extracellular space, extracellular matrix; Secreted
Pathways (Reactome):
Disease: Defective B3GALT6 causes EDSP2 and SEMDJL1; Defective B3GAT3 causes JDSSDHD; Defective B4GALT7 causes EDS, progeroid type; Defective CHST14 causes EDS, musculocontractural type; Defective CHST3 causes SEDCJD; Defective CHSY1 causes TPBS
Metabolism: CS-GAG biosynthesis; CS/DS degradation; DS-GAG biosynthesis; Glycosaminoglycan-protein linkage region biosynthesis
Extracellular matrix organization: Degradation of the extracellular matrix; ECM proteoglycans
Gene Ontology:
Molecular function: protein binding; RNA binding; extracellular matrix structural constituent conferring compression resistance; extracellular matrix binding; glycosaminoglycan binding
Biological process: negative regulation of angiogenesis; negative regulation of endothelial cell migration; negative regulation of vascular endothelial growth factor signaling pathway; positive regulation of autophagy; positive regulation of macroautophagy; positive regulation of mitochondrial depolarization; positive regulation of mitochondrial fission; positive regulation of phosphatidylinositol 3-kinase/protein kinase B signal transduction; positive regulation of transcription by RNA polymerase II; animal organ morphogenesis
Cellular component: extracellular matrix; extracellular region; elastic fiber; gel phase of interstitial matrix; Golgi lumen; lysosomal lumen
Genetic constraint (gnomAD): Loss-of-function variants: 9 observed, 19.92 expected, observed/expected ratio (o/e) 0.45, 90% interval 0.27 to 0.79. The upper end of that interval is the gene's LOEUF score, 0.79, which puts it in group 3 of 6, group 1 being the genes least tolerant of losing a copy. Missense variants: 253 observed, 289.87 expected, observed/expected ratio (o/e) 0.87, 90% interval 0.79 to 0.97. Synonymous variants: 109 observed, 110.77 expected, observed/expected ratio (o/e) 0.98, 90% interval 0.84 to 1.15.
Homologues: Orthologues: chimpanzee DCN (100% identical), macaque DCN (98% identical), dog DCN (93% identical), guinea pig DCN (91% identical), pig DCN (91% identical), rabbit DCN (91% identical), mouse Dcn (80% identical), rat Dcn (78% identical), tropical clawed frog dcn (75% identical), zebrafish dcn (67% identical). Paralogues in human: BGN (55% identical), ASPN (51% identical), PODN (25% identical), FLRT1 (24% identical), FLRT2 (23% identical), FLRT3 (23% identical), LRRTM1 (23% identical), PODNL1 (23% identical), LRRC15 (22% identical), LRRTM3 (22% identical), LRRTM4 (22% identical), NYX (21% identical), and 10 more.
Diseases named in the same sentence as DCN in open-access papers:
DCN is named in the same sentence as 323 diseases in open-access papers, as found by Europe PMC text mining. Sharing a sentence is not in itself a finding about the gene and the disease. The quoted sentences say what the papers report.
breast carcinoma (84 papers, 2008 to 2026). "Although decorin has differential expression across the breast cancer spectrum that appears to have clinical utility in DCIS risk stratification, it is not yet used clinically in DCIS." (PMID 39716322, 2024). "Conceptually, this would place decorin as a ROS modulator, compounds already implicated as pro-mitophagic as therapy for breast cancer." (PMID 35159071, 2022). "Specifically for breast cancer patients, low levels of decorin in the tumor microenvironment are associated with a more aggressive disease phenotype." (PMID 33924197, 2021). "Cawthorn and coworkers found that high decorin expression was associated with lymph node metastasis and poor clinical outcome in breast cancer; thus, decorin was proposed as an adverse prognostic and predictive biomarker." (PMID 32824864, 2020). "Lumican and decorin appeared to be inversely regulated in association with breast cancer tumourigenesis." (PMID 28332606, 2017). "CM of all colorectal cancer cell lines upregulated decorin expression, while CM of the majority of the breast cancer cell lines caused decorin suppression." (PMID 25593993, 2014). "In turn, breast cancer cells showed a significant enhanced spreading when plated on TGFβ1-treated, decorin-depleted, CAF-associated ECM." (PMID 25526025, 2014). "Previous studies have reported downregulation of decorin in breast cancer tissue, a situation which has been associated with a poor prognosis." (PMID 20398359, 2010). "Positive associations between decorin and lumican protein expression and mammographic density, a major risk factor for breast cancer, have also been observed." (PMID 19036156, 2008). "Decorin may also serve as an important diagnostic biomarker for patients with advanced stage (II or III) breast cancer as it emerged as an independent predictive factor for these stages." (PMID 35159071, 2022). "Furthermore, proteomic approaches have revealed an association between metastasis and decorin expression in breast cancer." (PMID 28653173, 2017). "Our data obtained using both phyllodes tumors and breast cancer cells raise the possibility that knockdown of periostin in cancer cells may cause an effect similar to that of decorin produced by fibroblasts and myofibroblasts." (PMID 25400079, 2014). "In addition, changes in CSPGs associated with breast cancer have been described, such as decorin or CSPG4." (PMID 23327652, 2013). "Furthermore, in breast cancer low expression of decorin has been shown to be associated with a shorter time to progression and a poorer survival." (PMID 24146840, 2013). "Moreover, abnormal decorin expression has been detected in mammographic density, a major risk factor for breast cancer, and array data have demonstrated decorin upregulation during mammary gland involution, likely contributing to increased collagenization." (PMID 23029096, 2012). "Associations with breast cancer risk for the DCN and LUM genes were observed with haplotype analyses in the Mayo Clinic sample." (PMID 19036156, 2008). "Lastly, associations between SNPs in ACAN/BGN/DCN genes and treatment characteristics may have an undetermined influence on our findings and should be explored in greater depth with breast cancer risk." (PMID 34162438, 2021). "By contrast, in breast cancer, high expression of either protein in tumour tissue, assessed by Western blots, was associated with good outcomes, and adenoviral overexpression of DCN or treatment with recombinant DCN have even been tested pre-clinically as therapies." (PMID 34253873, 2021). "As an example, in the selected breast cancer sample, top-scoring SVGs follow distinct patterns, exemplified by the genes decorin (DCN) and tyrosine aminotransferase (TAT)." (PMID 41160880, 2026). "In a study on breast cancer, plasma DCN was reported to be increased in more advanced stages, and also to be inversely associated with stromal DCN, but no survival analyses were performed." (PMID 41392017, 2026).
breast carcinoma (continued). "Decorin also suppresses bone metastasis in MDA-MB-231 breast cancer cells, and contributes to oppose cancer cell invasion as its stromal expression in breast invasive ductal carcinoma (IDC) is significantly weaker if compared to that in DCIS." (PMID 40643556, 2025). "Given its anti-metastatic and -tumorigenic effects, it is perhaps unsurprising that decorin has been found to have increased immunohistochemical expression in normal breast tissue (n = 97) compared to breast cancer (n = 187)." (PMID 39716322, 2024). "Elevated plasma levels of decorin were found to be an independent predictive factor for advanced breast cancer, while plasma glypican‐4 levels predicted 2‐year survival in metastatic breast cancer patients with an optimal cut‐off of 4.8 ng/mL." (PMID 39600538, 2024). "This indicates that breast cancer cells can downregulate DCN and activate NBFs in an IL-6-dependent manner, through the activation of STAT3/NF-κB signaling." (PMID 38667295, 2024). "This indicates that breast cancer cells can downregulate DCN in stromal fibroblasts through paracrine signaling." (PMID 38667295, 2024). "In fact, a meta-analysis study has shown that the low expression of stromal DCN predicts a bad prognosis in breast cancer patients." (PMID 38667295, 2024). "Next, we decided to investigate the effect of DCN downregulation on the paracrine pro-carcinogenic effects of fibroblasts on breast cancer cells." (PMID 38667295, 2024). "Decorin, a well-known tumor suppressor, frequently down-regulated in tumor tissues of prostate cancer, breast cancer, as well as CRC." (PMID 39306655, 2024). "After showing DCN-dependent inhibition of the secretion of several pro-carcinogenic cytokines from active CAF cells, we decided to investigate the effect of DCN upregulation on the paracrine pro-carcinogenic effects of CAFs on breast cancer cells." (PMID 38667295, 2024). "The soluble DCN protein core suppresses OXPHOS with a concurrent significant loss of MMP and evokes mitochondrial fragmentation and mitophagy via the DCN/Met/PGC-1α/mitostatin axis in breast carcinoma cells." (PMID 36438479, 2022). "Among these activators, decorin (DCN) has been shown to promote autophagy in various cells including endothelial, nucleus pulposus, and breast carcinoma cells." (PMID 35391926, 2022). "The downstream function of either Peg3 or mitostatin in response to decorin manifests as potent means to subdue breast cancer development and progression." (PMID 35159071, 2022). "Soluble decorin evokes protracted endothelial cell autophagy via Peg3 and breast carcinoma cell mitophagy via mitostatin by interacting with VEGFR2 or the MET receptor tyrosine kinase, respectively." (PMID 35159071, 2022). "Before delving into the discovery of decorin-mediated mitophagy in breast cancer, we will briefly review the general mechanism of decorin-evoked autophagy in endothelial cells as a starting point." (PMID 35159071, 2022). "On TAMs within murine mammary tumors, NRP2b was associated with increased markers of autophagy (MAPILC3A, DCN) as well as immunosuppression (PD-L1)." (PMID 35651620, 2022). "We then assessed if breast cancer cells treated with ionizing radiation had an altered paracrine effect on the expression of decorin of young and senescent human breast stromal fibroblasts." (PMID 33924197, 2021). "All breast cancer cell lines resulted in the decrease in decorin expression in both young and senescent human breast stromal fibroblasts." (PMID 33924197, 2021). "Further reinforcing the oncosuppressive role of DCN, systemic delivery of the DCN protein core or adenoviral transduction of DCN attenuated primary tumor growth and metastasis in breast cancer cells." (PMID 33452400, 2021).
breast carcinoma (continued). "Recent evidence suggests that bone metastatic breast cancer cells can reprogram osteoblasts in the bone marrow niche to produce altered amounts of decorin and CCN3, which leads to the inhibition of tumor cell proliferation via upregulation of p21 expression." (PMID 34831167, 2021). "Further studies are required to identify the mechanism of plasma DCN elevation in the advanced-stage breast cancer." (PMID 34884232, 2021). "Decorin expression levels of both young and senescent human breast stromal fibroblasts exposed to the conditioned medium of breast cancer cells untreated or treated with 4 and 10 Gy of ionizing radiation were similar." (PMID 33924197, 2021). "This study showed that plasma DCN levels were paradoxically elevated in patients with advanced-stage breast cancer despite the downregulation of local DCN in those with an early stage of invasive breast cancer." (PMID 34884232, 2021). "Many studies have demonstrated that DCN overexpression inhibits the progress of various tumors, such as breast cancer and colon cancer." (PMID 33820866, 2021). "We analyzed the stromal and systemic expressions of DCN and compared them to the pathological stages of the patients with breast cancer." (PMID 34884232, 2021). "Consistent with our previous report, the expression of stromal DCN was attenuated in breast cancer with invasive components even when the disease was still early." (PMID 34884232, 2021). "Studies have found that DCN can inhibit the proliferation and migration of a variety of tumour cells in vitro, such as liver cancer, kidney cancer and breast cancer." (PMID 32319226, 2020). "Virus-delivered decorin attenuated breast cancer growth and prevented its metastasis formation in various organs." (PMID 32477937, 2020). "Our findings are in accordance with earlier reports where adenovirus-mediated decorin gene delivery inhibited the proliferation of colon and squamous carcinoma, urothelial malignancies, prostate cancer, breast cancer bone metastases and pancreatic tumor." (PMID 32824864, 2020). "Adenovirus overexpression of IL-12 and decorin have demonstrated potent antitumor effects in a weakly immunogenic murine model of breast cancer." (PMID 32082161, 2019). "We next wanted to determine if the rescue of decorin or NOV expression to that of expression levels seen in vehicle-treated osteoblasts would increase breast cancer cell proliferation." (PMID 30813947, 2019). "DCN was found underexpressed in breast cancer, colon cancer, follicular thyroid cancer, and follicular variant of papillary thyroid carcinomas." (PMID 31583243, 2019). "Oncolytic adenovirus expressing decorin significantly inhibited the progression of bone metastases in MDA-MB-231 metastasis model of breast cancer." (PMID 32082161, 2019). "On the other hand, triple-negative orthotopic breast carcinoma systemic treatment with the proteoglycan decorin induced the tumor suppressor cell adhesion molecule 1 (Cadm1), favoring a less metastatic phenotype." (PMID 31157165, 2019). "In a similar fashion, since the expression of decorin was reduced in the CM of EO cells compared to the CM of vehicle-treated osteoblasts, we treated breast cancer cells with EO CM plus recombinant decorin protein." (PMID 30813947, 2019). "CAF-derived proteoglycans, as decorin, further suppress immunomodulatory genes in triple-negative orthotopic breast carcinoma xenografts, including Siglec (Sialic acid binding Ig-like lectin), Lipg (IFNγ inducible GTPase), and Il1b (Interleukin 1β)." (PMID 31157165, 2019). "Serial sections of human patient samples of bone metastatic breast cancer were stained using immunofluorescence for decorin (yellow), NOV (yellow), and osteopontin (OPN, red)." (PMID 30813947, 2019). "Decorin is a protein with anti-tumor properties and was explored as an anti-tumor agent in breast cancer." (PMID 30813947, 2019).
breast carcinoma (continued). "Restoration of decorin protein in the CM of EO cells increased breast cancer cell proliferation to levels comparable of exposure to the vehicle-treated osteoblast CM (orange line)." (PMID 30813947, 2019). "Quite recently we have also shown that human ductal, lobular and mucinous breast cancer cells lack decorin synthesis." (PMID 28653173, 2017). "This supports previous findings that DCN is down-regulated and influences the breast cancer cell motility and invasion, and acts as one of the six-gene signature that adds prognostic value independent of the expression of ER, PR, and HER2." (PMID 28052038, 2017). "We previously discovered that systemic delivery of decorin for treatment of breast carcinoma xenografts induces paternally expressed gene 3 (Peg3), an imprinted gene encoding a zinc finger transcription factor postulated to function as a tumor suppressor." (PMID 28174297, 2017). "In cancers, including breast cancer, the expression of decorin in the TME has been reported to be markedly decreased or totally lacking in malignant cells." (PMID 28653173, 2017). "Reduced expression of decorin has also been observed in breast cancer tissues compared with normal tissues." (PMID 28083513, 2016). "Treatment of A431 squamous cell carcinoma and breast carcinomas transfected with DCN cDNA resulted in tumor cell apoptosis, reduced EGFR signaling, and retarded tumor growth." (PMID 26697491, 2015). "In breast cancer, collagen accumulation together with increased expression of small leucine-rich proteoglycans (SLRPs) decorin and lumican has been shown to correlate with increased mammographic density." (PMID 26056582, 2014). "In breast cancer, reduced stromal decorin correlates with the myxoid stromal architecture, both are associated with increased recurrence risk in DCIS and propensity to progress to invasive ductal carcinoma (IDC)." (PMID 25526025, 2014). "In this study, we characterized the interaction between cellular decorin and periostin not only in phyllodes tumors but also in BT-20 breast cancer cells." (PMID 25400079, 2014). "In order to analyze published data on decorin gene expression in different types of human breast cancer, we used an in silico database from the GeneSapiens website." (PMID 23007289, 2013). "Studies utilizing decorin transduction have previously been conducted e.g. with breast cancer cells and the results have shown both reduced primary tumour growth and prevention of metastasis." (PMID 24146840, 2013). "We have also examined the influence of adenoviral mediated decorin transduction on the behavior of human breast cancer cells in vitro." (PMID 23007289, 2013). "Recently, we have shown that different types of human breast cancer cells totally lack decorin mRNA." (PMID 24146840, 2013). "We also examined the effect of decorin transduction on the behavior of cultured human breast cancer MCF7 cells." (PMID 23007289, 2013). "Next, we localized decorin mRNA in tissue specimen of normal human breast, intraductal breast papillomas and various histologic types of human breast cancer using in situ hybridization (ISH) with digoxigenin-labeled RNA probes for decorin." (PMID 23007289, 2013). "Here, we first compared decorin gene expression levels between healthy human breast tissue and selected types of human breast cancer using GeneSapiens databank." (PMID 23007289, 2013). "Using an animal model of orthotopic breast carcinoma, decorin has also been shown to slow mammary carcinoma cell motility, induce significant apoptosis and impede cell invasion through a three-dimensional extracellular matrix." (PMID 23007289, 2013). "We have also shown that the adhesion, proliferation and apoptosis of MCF-7 human breast cancer cells can be influenced by decorin transduction." (PMID 24146840, 2013). "Analysis of GeneSapiens databank revealed that in various human breast cancers decorin expression is significant." (PMID 23007289, 2013).